PDGFRB (platelet derived growth factor receptor beta)
Diseases named in the same sentence as PDGFRB in open-access papers (continued):
Sharing a sentence is not in itself a finding about the gene and the disease.
epidermal nevus (1 paper, 2024). "Sequence analysis from DNA extracted from both the LM lesion, the epidermal nevus lesion and peripheral blood shows a profile of a germline PTEN pathogenic variant (c.962delC, p.Thr321fs) and a germline PDGFRB (c.2T > G) variant." (PMID 39080810, 2024).
epithelioid sarcoma (1 paper, 2024). An aggressive malignant neoplasm of uncertain differentiation, characterized by the presence of epithelioid cells forming nodular patterns. "Additionally, more than 55% of patients with epithelioid sarcoma exhibited high marker expression with PDGFRβ." (PMID 39534097, 2024).
erythroleukemia (1 paper, 2024). Acute erythroid leukemia characterised by the presence of at least 50% erythroid precursors and at least 20% myeloblasts in the bone marrow. "Consistently, the Gene Ontology (GO) and Kyoto Encyclopedia of Genes and Genomes (KEGG) pathway analysis of these DEGs, using ClueGO, also showed that the glycosaminoglycan biosynthetic process and PDGFRB signaling pathway were strongly associated with the anti-erythroleukemia effect of BW18." (PMID 38794198, 2024). "Taken together, our findings elucidated a novel role of PDGFRB in regulating erythroleukemia differentiation and highlighted BW18 as an attractive lead compound for erythroleukemia treatment." (PMID 38794198, 2024). "We then explored whether BW18-induced erythroleukemia differentiation was mediated in a PDGFRB-dependent manner." (PMID 38794198, 2024). "An analysis of BW18-related DEGs from RNA-seq suggested that the PDGFRB signaling pathway might be an important mediator for the anti-erythroleukemia of BW18." (PMID 38794198, 2024). "These beneficial effects can be explained by the BW18-mediated inactivation of PDGFRB and JAK2/STAT3 pathway in erythroleukemia cells." (PMID 38794198, 2024).
focal epilepsy (1 paper, 2019). A seizure caused by a localized disorder. "All of the patients had refractory focal epilepsy and it is likely that seizures influence the baseline glial populations, including densities of nestin 8, PDGFRβ+ glial cells 41, 42 and Cx43 expression on astrocytes 24 in Zone 3 used as the control region as in previous studies." (PMID 30636077, 2019).
focal segmental glomerulosclerosis (1 paper, 2024). A renal disorder characterized by sclerotic lesions in the glomeruli. "Intraglomerular Pdgfrβ expression was also corroborated by another independent study, which showed robust Pdgfrβ upregulation in the cells occupying glomerular Bowman’s space triggered by focal segmental glomerulosclerosis." (PMID 39184103, 2024).
Granuloma (1 paper, 2017). A compact, organized collection of mature mononuclear phagocytes, which may be but is not necessarily accompanied by accessory features such as necrosis. "Of interest, granuloma nodules in the heart showed similar accumulation of podoplanin and PDGFRβ co-presenting cells." (PMID 28333941, 2017). "In the infarcted myocardium with no granulomas, the high occurrence of PDGFRβ in podoplanin-bearing cells was apparent as well, albeit at the later stages of wound repair, concomitantly with the scar development." (PMID 28333941, 2017).
Hematochezia (1 paper, 2021). The passage of fresh (red) blood per anus, usually in or with stools. "We here describe an infant with PDGFRB-driven IM with multiple tumors at different sites, including intestinal polyposis with hematochezia, necessitating temporary chemotherapy." (PMID 34132909, 2021).
hemorrhage (1 paper, 2024). Loss of blood from the vascular compartment to the exterior or into nonvascular body space as a result of rupture or severance of the blood vessels. "In our research, we observed fusiform-like cerebral vascular dilatation, cerebrovascular malformations and intracranial hemorrhages phenotypes in developing zebrafish transfected with PDGFRB mutations." (PMID 38741091, 2024).
Hydrocephalus (1 paper, 2016). Hydrocephalus is an active distension of the ventricular system of the brain resulting from inadequate passage of CSF from its point of production within the cerebral ventricles to its point of absorption into the systemic circulation. "Here we show that PDGFRβ+ pericyte-derived laminin is abrogated in all conditional knockout mice, but only 10.7% demonstrate CNS phenotype, including hydrocephalus and BBB breakdown." (PMID 27808256, 2016). "It should be noted that laminin expression is absent in PDGFRβ+ cells from all PKO mice, whereas only 10.7% show brain abnormality (hydrocephalus and BBB breakdown)." (PMID 27808256, 2016).
IgA nephropathy (1 paper, 2022). "We previously reported that TNC was significantly increased in injured glomeruli of IgA nephropathy and expressed by PDGFRβ positive mesangial cells." (PMID 36522320, 2022).
inflammatory myofibroblastic tumor (1 paper, 2022). A multinodular intermediate fibroblastic neoplasm that arises from soft tissue or viscera, in children and young adults. "Inflammatory myofibroblastic tumor fusions involving ROS1, PDGFRβ, RET, and NTRK have also been described in inflammatory myofibrosarcoma." (PMID 35865478, 2022).
Kawasaki disease (1 paper, 2024). A rare inflammatory disease characterized by an acute febrile, systemic, self-limiting, medium-vessel vasculitis primarily affecting children. "Platelet-derived miR223 inhibits VSMC differentiation and restores Kawasaki-disease-induced vascular injury through the inhibition of PDGFRβ; miR143 and miR145 target Krüppel-like factor (KLF) 4 and 5, respectively, to suppress VSMC dedifferentiation." (PMID 39595622, 2024). "Thus, targeting the miR223/PDGFRβ axis may provide a novel therapeutic option for Kawasaki-disease-induced vascular pathologies." (PMID 39595622, 2024).
large granular lymphocyte leukemia (1 paper, 2019). "Interestingly, aberrant autocrine activation of PDGFRB has been shown in large granular lymphocyte leukemia which presents as T-cell or NK-cell malignancy, highlighting the role of PDGFRB in the context of deregulated T-/NK-cell differentiation." (PMID 31143370, 2019).
leukodystrophy (1 paper, 2021). Leukodystrophies are a group of rare, progressive, metabolic, genetic diseases that affect the brain, spinal cord and often the peripheral nerves. "Expression of selective neurovascular unit markers such as claudin-5, zona occludens 1, laminin, PDGFRβ, aquaporin-4 and α-dystroglycan was investigated in eight different leukodystrophies using immunohistochemistry." (PMID 34082828, 2021). "We chose one or more leukodystrophy patient representative of each disease category, and investigated expression of claudin-5, ZO-1, laminin, PDGFRβ, α-dystroglycan and AQP4 together with UEA I and/or GFAP." (PMID 34082828, 2021).
limb ischemia (1 paper, 2022). A ischemia that involves the limb. "Leptin is reportedly expressed by perivascular PDGFRβ+ cells and contributes to transplanted PCs’ proangiogenic activity in a mouse model of limb ischemia." (PMID 35349488, 2022).
lung carcinoid (1 paper, 2017). "One patient with lung carcinoid with Ki-67 < 5% without evidence of an inherited syndrome had somatic mutations detected including PDGFRB A366T and CDKN1b loss, and had best response of stable disease on treatment." (PMID 29262620, 2017).
malaria (1 paper, 2021). Malaria is a serious and sometimes fatal disease caused by a parasite that commonly infects a certain type of mosquito which feeds on humans. "In order to directly establish the potential biological importance of the TRAP:PDGFRβ interaction, we initially attempted to block the interaction in vivo and measure the effect on sporozoite transmission success, using the P. yoelii mouse malaria model." (PMID 34059712, 2021). "While the biological consequences of the TRAP:PDGFRβ interaction remain to be fully deciphered, our work provides a novel molecular interaction lead that could mediate the initial infection of the human host by malaria parasites." (PMID 34059712, 2021).
malignant phyllodes tumours (1 paper, 2025). "Both patients with malignant phyllodes tumours and pathogenic PDGFRB and PIK3CA mutations received multi-thyrosine kinase inhibitor therapy but died of the disease." (PMID 40144205, 2025). "Two additional patients with malignant phyllodes tumours had pathogenic PDGFRB and PIK3CA mutations, respectively)." (PMID 40144205, 2025).
Marfan syndrome (1 paper, 2009). A disorder of the connective tissue. "Taken together, our findings suggest that aorta elongation and elastic layer disruption, both hallmarks of Marfan syndrome, require the PDGFRβ dependent activation of PI3K." (PMID 19742316, 2009). "Suppression of PI3K activation by PDGFRβ prevents the Marfan-like phenotypic changes in the vascular wall in the presence of unabated TGFβ signaling, suggesting a pivotal role of LRP1-controlled and PDGFRβ-dependent PI3K activation in the pathogenesis of Marfan syndrome." (PMID 19742316, 2009).
metastatic cancer (1 paper, 2021). A carcinoma which has spread from the original site of growth to another anatomic site. "The PDGFRβ inhibitor imatinib, which has been approved for the treatment of malignant metastatic cancer, protected mice against JEV-induced lethality by decreasing the viral load in the brain while abrogating the histopathological changes associated with JEV infection." (PMID 33753340, 2021).
nasopharyngeal carcinoma (1 paper, 2022). A carcinoma arising from the nasopharyngeal epithelium. "Therefore, circRNA-000543 knockdown could sensitize nasopharyngeal carcinoma cells to radiation by targeting the miR-9/ PDGFRB axis." (PMID 36358938, 2022).
neural tumors (1 paper, 2025). "Overall, by comparing to PA, we identified subtype-specific pathways in neural tumors: PAK signaling (PTPRD and PDGFRB) in GBM, regulation of CFTR activity pathway (PPP2R1A, RABEP1) in MBL, and ERK signaling (IRS4 and ATM) in NBL." (PMID 40768543, 2025).
neuro-degenerative diseases (1 paper, 2022). "Besides AD, studies reported the links between PDGFRB and other neuro-degenerative diseases." (PMID 35615282, 2022).
Nijmegen breakage syndrome (1 paper, 2017). Nijmegen breakage syndrome is a rare genetic disease presenting at birth with microcephaly, dysmorphic facial features, becoming more noticeable with age, growth delay, and later-onset complications such as malignancies and infections. "Genetic analyses were performed and revealed a PDGFRB gene c.1681C>A missense heterozygous germline mutation, high PDGFRβ phosphokinase activity within the tumor and the heterozygous germline Slavic Nijmegen breakage syndrome 657del5 mutation in the NBN gene." (PMID 28183292, 2017).
oncocytoma (1 paper, 2019). "ErbB4, Insulin R, and IGF-1R were phosphorylated in the papillary RCC (RE0020), Mer (Axl family) was phosphorylated in the oncocytoma (RE0150), and HGFR, PDGFRα, and PDGFRβ were phosphorylated in the renal pelvic carcinoma (RE0210)." (PMID 31690270, 2019).
oropharyngeal cancer (1 paper, 2020). Carcinoma, predominantly squamous cell, arising from the epithelial cells of the oropharynx. "PDGFB binds to PDGFRB and is speculated to play a crucial role in the tumorigenesis of oropharyngeal cancer." (PMID 32235327, 2020).
osteonecrosis of (1 paper, 2023). "The Venn diagrams showed six intersecting genes related to osteonecrosis of the femoral head, OS and APO targets: NFE2L2 (Nrf2), ERN1, PDGFRB, PDGFRA, KEAP1 and CDK1." (PMID 37749949, 2023).
papilloma (1 paper, 2022). A benign epithelial neoplasm that projects above the surrounding epithelial surface and consists of villous or arborescent outgrowths of fibrovascular stroma. "We found that the mRNA levels of αSMA and PDGFRβ, markers of activated myofibroblasts and CAFs, were significantly lower in the Itga11−/− papillomas as compared with the Itga11+/+ papillomas." (PMID 36003785, 2022). "However, the quantification of signal intensities did not reveal significant differences in PDGFRβ or αSMA expression between the Itga11−/− and Itga11+/+ papillomas." (PMID 36003785, 2022).
pseudohypoparathyroidism (1 paper, 2024). "Despite the thorough analysis, no known pathogenic variants were found in genes typically associated with Fahr’s syndrome (e.g., XRP1, PDGFRB, JAM2, PDGFB, SLC20A2, or MYORG) or pseudohypoparathyroidism (e.g., GNAS, STX16, or GNASAS1)." (PMID 39519162, 2024).
pulpitis (1 paper, 2023). Inflammation of the dental pulp. "We also revealed that the removal of Pdgfrβ+ pericytes induced pulpitis-like pathological features in mice." (PMID 38137420, 2023).
rectal tumors (1 paper, 2020). "Moreover, high expression levels of PAI1 are associated with increased metastasis and invasion of rectal tumors in this cohort and TCGA database, respectively, which is correlated with EMT-associated and drug target genes expression, including PDGFRa, PDGFRb, FYN, PIM1 and BRAF." (PMID 32344898, 2020).
Right ventricular hypertrophy (1 paper, 2022). In this case the right ventricle is more muscular than normal, causing a characteristic boot-shaped (coeur-en-sabot) appearance as seen on anterior- posterior chest x-rays. "It decreased PDGFRβ mRNA level and medial wall thickness of fully muscularized vessels but did not improve right ventricular hypertrophy nor did it reduce pulmonary arterial muscularization." (PMID 35629326, 2022).
synucleinopathies (1 paper, 2025). "PDGFRβ signalling has been described as altered in some neurodegenerative disorders, including AD and synucleinopathies." (PMID 40239464, 2025).
testicular tumor (1 paper, 2018). "Resistant cells recover their sensitivity to CDDP when levels of p-AKT are reduced by PI3K inhibitor Ly294002, suggesting that p-AKT may be an essential player for CDDP resistance in testicular tumor cells, following the signal pathway regulated by PDGFRβ." (PMID 29416701, 2018).
thymic lymphoma (1 paper, 2022). "Murine thymic lymphoma cells lacking PDGFRβ proliferate at slower rates both in vitro and when implanted subcutaneously into NSG mice." (PMID 36045346, 2022).
thymoma (1 paper, 2017). A neoplasm arising from the epithelial cells of the thymus. "A low PDGFRB expression was noted in 40 % of type A and 12 % of B3 thymomas." (PMID 27844328, 2017).
urinary system cancer (1 paper, 2014). "Indeed, EGF/EGFR, FGFR2, KLK3, and PDGFRB were reported to play important roles in urinary system cancer development and progression." (PMID 24801713, 2014).
vascular tumors (1 paper, 2022). "Apart from the PI3K/AKT/MTOR and RAS/RAF/ERK signaling pathways, other signaling pathways are also involved in VAs: VEGF-A/VEGFR2 signaling and PDGFB/PDGFRB Signaling Pathway in vascular tumors (IH) and HGF [hepatocyte growth factor])/c -Met signaling in glomuvenous malformations (GVMs)." (PMID 36293054, 2022).
tumor (1,249 papers, 2004 to 2026). "The receptor tyrosine kinase encoded by PDGFRB plays a pivotal role in tumor stroma activation and angiogenesis." (PMID 41601676, 2026). "High expression of PDGFRβ in tumour stroma was associated with large tumour size, advanced stage, and high vessel density in prostate cancer." (PMID 39780187, 2025). "This indicates that a higher tumor stemness index is associated with greater expression of PDGFRB, which correlates with a worse prognosis." (PMID 40128057, 2025). "Somatic mutations associated with the hepatic fibrosis pathway included missense mutations in several COSMIC driver genes including PDGFRB (VAF = 0.020 to 0.053 in HCC tumor regions) and PTCH1 (VAF = 0.019 in HCC tumor)." (PMID 40340757, 2025). "Based on an index case, we found recurrent PDGFRB gain-of-function mutations as the oncogenic driver in a cohort of dermatomyofibromas, adding these neoplasms to the protein kinase-related tumors." (PMID 40387903, 2025). "Overexpression of PDGFRα and PDGFRβ was significantly associated with unfavorable tumor characteristics and higher tumor burden." (PMID 40434293, 2025). "PDGFRβ signaling in pericytes has been implicated in both tumor growth and metastasis, suggesting potential therapeutic opportunities to be further explored." (PMID 38980580, 2024). "CAFs, identified based on the expression of fibroblast-associated markers such as FAP, CD90, and PDGFRβ, play a central role in influencing the tumor immune response." (PMID 39834587, 2024). "Spatial mapping further associates low MC tumor regions with immune escape, mediated by PDGFRB signaling activating the downstream immunosuppressive LAG3/FGL1 axis." (PMID 39015573, 2024). "In both studies, loss of PDGFRβ-positive perivascular cells induced a pro-metastatic vascular phenotype, including increased hypoxia, c-Met-dependent tumor cell stimulation, and increased angiopoietin-2-dependent angiogenesis." (PMID 38980580, 2024). "Platelet-derived growth factor receptor β (PDGFRβ) is the representative biomarker on the surface of tumor-associated pericytes." (PMID 37256321, 2023). "The expression of T-cell-related PDGFRB was associated with tumor microenvironment, which significantly downregulated after chemotherapy treatment." (PMID 37745978, 2023). "PDGFRB+ cancer-associated fibroblasts (CAFs) are an important component of stromal cells in the tumor microenvironment." (PMID 35967414, 2022). "PDGFRB is a cell surface tyrosine kinase receptor for members of the platelet-derived growth factor family and is involved in the regulation of multiple tumor-associated processes including tumor progression, angiogenesis, and regulation of tumor fibroblasts." (PMID 36139587, 2022). "In particular, the binding of PDGF-D to its cognate receptor PDGFRβ, expressed by CAFs, triggers a series of biochemical events that sustain tumor-associated lymphangiogenesis and tumor cell dissemination." (PMID 35887583, 2022). "The Bcl-2 family protein enhances susceptibility to CAF apoptosis and PDGFRβ induces fibroblast migration and stimulates tumor lymphangiogenesis." (PMID 36362726, 2022). "The most important features positively correlated with PDGFRB mutation were sex, mMIXED – corresponding to the proportion of the mixed tissue in the tumor microenvironment – and tTUMOR – corresponding to the fraction of the entire slide occupied by the tumor." (PMID 36131239, 2022). "In VHL-inactive ccRCC, histone lactylation is likely to act as a bridge between VHL deficiency and PDGFRβ hyperactivation to support tumor progression." (PMID 35637958, 2022). "Three cancer census genes, FOXO4 (NM_005938: p.S71C), GNAQ (NM_002072: p.T96S) and PDGFRB (NM_002609: p.V568E), acquire mutations as the tumor progresses to malignancy." (PMID 34816314, 2022).